VEGFA (vascular endothelial growth factor A)
Diseases named in the same sentence as VEGFA in open-access papers (continued):
Sharing a sentence is not in itself a finding about the gene and the disease.
atherosclerosis (319 papers, 2008 to 2026). A disease characterized by the build-up of fatty material and calcium deposition in the arterial wall resulting in partial or complete occlusion of the arterial lumen. "VEGFA is positively correlated with elevated blood pressure and is strongly associated with vascular damage and atherosclerosis." (PMID 38496269, 2024). "Animal studies have also shown that overexpression of VEGFA increases the likelihood of atherosclerosis in ApoE-deficient mice." (PMID 38089766, 2023). "Vascular remodeling during atherosclerosis was also associated with the expression of VEGFA, which has the effect of inducing angiogenesis, promoting their survival, and enhancing vascular permeability." (PMID 37076581, 2023). "Atherosclerosis is associated with important signaling pathways, such as the vascular endothelial growth factor A-vascular endothelial growth factor receptor 2 (VEGFA-VEGFR2) signaling pathway." (PMID 38130647, 2023). "The hypoxia-induced VEGFA signaling pathway is closely associated with ischemic cerebrovascular disease, affecting atherosclerosis and intrinsic collateral circulation, and is involved in cerebral infarction pathogenesis." (PMID 35668929, 2022). "In the PDGF-BB-stimulated atherosclerosis model, it was discovered that circLMF1 deficiency inhibited cell survival, cell cycle progression, and migration, possibly via the miR-125a-3p/VEGFA or FGF1 axis." (PMID 35607519, 2022). "Notable increases in VEGFA+ macrophages were discovered in the disturbed flow stimulation group, displaying a pronounced M1 pro-inflammatory phenotype associated with the severity of atherosclerosis and plaque stability." (PMID 40594772, 2025). "VEGFA+ macrophages were increased in the disturbed flow stimulation group, displaying pronounced M1 pro-inflammatory phenotype associated with the severity of atherosclerosis and plaque rupture." (PMID 40594772, 2025). "In a PDGF-BB-stimulated atherosclerosis model, the researchers discovered that circLMF1 deficiency was found to suppress cell survival, cell cycle progression, and migration, possibly via the miR-125a-3p/VEGFA or FGF1 axis." (PMID 35607519, 2022). "ATR could act on the KDR gene, which is one of the key molecules related to angiogenesis and a strong risk factor for atherosclerosis, while CR can act on its ligand VEGFA." (PMID 32802132, 2020). "In this study, EGFR, VEGFA, HSP90AA1, SRC, HIF1A, CXCR4 and IGF1R were identified as key hub targets, which linked anthocyanins with atherosclerosis." (PMID 40478326, 2025). "We further conducted Gene set enrichment analysis (GSEA) using the VEGFA+ macrophage TOP 50 genes as geneset to characterize the role of VEGFA+ macrophages in atherosclerosis." (PMID 40594772, 2025). "We found CD36+ endothelial cells, VEGFA+ macrophages and adventitial fibroblasts play critical roles in the occurrence and progression of atherosclerosis." (PMID 40594772, 2025). "Analysis of GSE71226 and GSE9128 expression data of atherosclerosis group revealed that VEGFA was downregulated, while MMP9 and IL-1β were upregulated." (PMID 37880698, 2023). "This study also showed that miR-152 has a target relationship with VEGFA that is an important signal molecule leading to atherosclerosis." (PMID 35345660, 2022). "Studies have shown that vascular remodeling during atherosclerosis is related to the expression of VEGFA." (PMID 34746316, 2021). "ANGPTL3 induced angiogenesis with a magnitude comparable to vascular endothelial growth factor-A, which promotes intimal thickening and induces atherosclerosis." (PMID 32280540, 2020). "In this study, we found VEGFA + macrophage may be an important contributor of VEGFA in atherosclerosis plaques." (PMID 40594772, 2025). "CD36+ ECs, VEGFA+ macrophages, and adventitial fibroblasts play critical roles in atherosclerosis." (PMID 40594772, 2025). "Cluster analysis emphasized IL6, TNF, AKT1, and VEGFA’s roles in atherosclerosis and inflammation." (PMID 38496269, 2024).
atherosclerosis (continued). "However, VEGFR1 demonstrates a dual action, playing a negative role in angiogenesis in the embryo, most likely by trapping VEGFA, while it plays a positive role in macrophage function, inflammation, and atherosclerosis in adulthood." (PMID 36835220, 2023). "Here, we present data indicating that many atherosclerosis and cardiovascular risk-related proteins that were found to be up-regulated in other Olink studies (e.g., SELE/E-selectin, TNFSF14/LIGHT, VEGFA, RETN/resistin, MMPs) are in fact suppressed by dupilumab in tape-stripped skin lesions." (PMID 32849633, 2020). "Our study suggested that targeting TNK2‐AS1/miR‐150‐5p/VEGFA/FGF1 axis may be effective in attenuating atherosclerosis." (PMID 31468685, 2019). "Moreover, the shift in the balance between M1-like VEGFA+ and M2-like Lyve1+ macrophages may play a critical role in the progression of atherosclerosis." (PMID 40594772, 2025). "Vascular endothelial growth factor A (VEGFA) and its main receptor VEGFR2 are key mediators in atherosclerosis, as they regulate endothelial responses to inflammation and damage." (PMID 40869165, 2025). "Gene Expression Omnibus (GEO) validation demonstrated that VEGFA was downregulated, while MMP9 and IL-1β were upregulated in patients with atherosclerosis." (PMID 37880698, 2023). "The results were validated using ClueGo + Pedia apps, and the “Fluid shear stress and atherosclerosis” pathway, including the three genes (IL-1β, MMP9, VEGFA), were the target genes in the eight hub genes." (PMID 37880698, 2023). "Previous studies have shown that VEGFA, EGFR, and FGF2 are related to vascular endothelial regeneration, and that vascular endothelial cell damage is a significant feature of atherosclerosis." (PMID 36212940, 2022). "There were six targets in the intersection with 137 candidate therapeutic targets of XFZYD, which included upregulated PTGS2, MMP9, and BCL2L1 and downregulated JUN, VEGFA, and CXCL2 in the atherosclerosis group." (PMID 33425996, 2020). "Together, our findings show that Sema7A promotes VEGFA/VEGFR2-mediated neovascularization in a β1 integrin-dependent manner, supporting a crucial role of Sema7A in the progression of human atherosclerosis." (PMID 30555351, 2018). "Finally, eight hub genes were identified, and IL-1β, VEGFA, and MMP9 genes in the fluid shear stress and atherosclerosis pathway are the most likely target genes in treating atherosclerosis." (PMID 37880698, 2023). "Therefore, in this study, lipid levels, SOD activity, ROS activity, VEGFA, and MMP-2 expression were measured in mice with CHD to assess the effect of EGCG on the formation as well as progression of atherosclerosis." (PMID 35919501, 2022). "Moreover, VEGFA/VEGFR2, upstream of the MAPK/ERK signaling pathway, has been confirmed to facilitate intraplaque neovascularization in atherosclerosis." (PMID 35155448, 2021). "BCAR1 may be affected by coxibs via other, pleiotropic mechanisms, but – like VEGFA and MMP9 – this gene has been studied functionally in the context of atherosclerosis before." (PMID 28860667, 2017). "The results of fluid shear stress and atherosclerosis enrichment pathway, AGE-RAGE signaling pathway, and PPI core protein ranking showed that VEGFA and AKT1 are closely related to the development of AS, and maybe the key regulatory proteins of XFZYD in the treatment of AS." (PMID 35960089, 2022). "Vascular endothelial growth factor A (VEGFA) is a special type of cytokine, which is secreted by various cells such as vascular endothelial cells, and plays an important role in regulating blood vessel formation, tumor growth and development and atherosclerosis." (PMID 34778698, 2021).
atherosclerosis (continued). "NADPH oxidase-derived superoxide has also been shown to modulate the vascular endothelial growth factor A (VEGF-A) signaling pathway, suggesting a link between increased NADPH oxidase activation and increased endothelial migration and proliferation that occurs during atherosclerosis." (PMID 25705646, 2014). "Our results presented new evidence that activated platelets could remotely modulate ET-1 and VEGFA expression in HUVEC via releasing miR-200a-3p-enriched PMVs, which provides a potential miRNA-based predictive biomarker and therapeutic strategy for atherosclerosis and AIS." (PMID 35755441, 2022). "In summary, we discovered that activated platelets could remotely modulate ET-1 and VEGFA levels in vascular endothelial cells through the release of miR-200a-3p-containing PMVs via targeting MAPK14, which provides a potential miRNA-based therapeutic strategy for atherosclerosis related diseases." (PMID 35755441, 2022).
preeclampsia (307 papers, 2008 to 2026). Preeclampsia is a hypertensive disorder of pregnancy that is characterized by new-onset hypertension with proteinuria presenting after 20 weeks of gestation, and depending on mild or severe forms may initially present with severe headache, visual disturbances, and hyperreflexia. "The suppression of VEGFA by miR-26a-5p leads to reduced trophoblast proliferation and invasion, potentially contributing to complications such as preeclampsia, where inadequate placental development is a hallmark." (PMID 39595182, 2024). "VEGFA has been implicated in the pathophysiology of pre-eclampsia (PE), since pre-eclamptic women present with reduced levels of free circulating VEGFA." (PMID 36941544, 2023). "Among others, vascular endothelial growth factor A (VEGF-A) is an important target of miRNA-26a-5p and reduced VEGF-A levels are a hallmark of preeclampsia." (PMID 34502062, 2021). "The major finding from the current study is the significant association between a VEGFA gene polymorphism and preeclampsia." (PMID 31943890, 2020). "In this study, we detected an association between preeclampsia and VEGFA and IL1β gene polymorphisms." (PMID 31943890, 2020). "Anti-angiogenic factorsthat reduce the amount of VEGF-A is one of the factorsinhibiting formation of spiral arteries, which eventuallyassociated with the creation of preeclampsia.VEGFA is one of the factors encoded by VEGF gene." (PMID 32681623, 2020). "F5 (OMIM# 612309), MTHFR (OMIM# 607093) and VEGFA (OMIM# 192240) genes have been widely studied in association with preeclampsia." (PMID 31646966, 2019). "VEGFA variants have been widely studied and its association with preeclampsia has been found in several studies, including Chinese, Brazilian, Hungarian and Korean patients." (PMID 31646966, 2019). "Polymorphisms in IL1β and VEGFA were associated with preeclampsia in this setting." (PMID 31943890, 2020). "There are few published data regarding the association of VEGFA and IL1β polymorphisms with preeclampsia, and there are no published data regarding the association of VEGFA and IL1β polymorphisms were preeclampsia in sub‐Saharan African populations, including in Sudan." (PMID 31943890, 2020). "However, our study negates the association of VEGFA: c.-2055A > C and c.*237C > T variants with preeclampsia in Pakistani patients." (PMID 31646966, 2019). "Preeclampsia involves an angiogenic imbalance, but circulating vascular endothelial growth factor A (VEGF A) remains inconsistently described, particularly in relation to maternal adiposity." (PMID 41828656, 2026). "This is consistent with emerging evidence in other diseases, such as preeclampsia, where miRNAs such as miR-510-3p effectively regulate disease progression by targeting VEGFA and related pathways." (PMID 40760228, 2025). "Decreased expression of VEGFA, PGF, and KDR mRNA in placentas from pregnancies complicated by gestational hypertension was also observed, as well as reduced expression of VEGFA mRNA in placentas from pregnancies complicated by SGA with normal pressure." (PMID 38238614, 2024). "Preterm infants with clinical chorioamnionitis and placental inflammation had higher classical and intermediate monocyte VEGFA gene expression and plasma VEGFA concentration than preterm infants with preeclampsia and MVM." (PMID 35471950, 2022). "Applying these findings to a mouse model, a TLR9 agonist induced the traditional hallmarks of preeclampsia and also reproduced the downregulated VEGFA and elevated sFLT-1 observed in human tissue." (PMID 34831277, 2021). "HIF-1α (in hypoxic conditions) has been shown to increase VEGFA expression, while a reduction in VEGF has been observed in placentae from complicated pregnancies such as preeclampsia." (PMID 31178743, 2019). "In the present study, 6 SNVs of F5, MTHFR, and VEGFA genes have been studied in patients with preeclampsia and normal controls." (PMID 31646966, 2019).
preeclampsia (continued). "The common SNVs found in association with preeclampsia include F5:c.1601G > A (rs6025), MTHFR: c.665C > T (rs1801133), MTHFR: c.1286A > C (rs1801131), VEGFA: c.-2055A > C (rs699947) and VEGFA: c.*237C > T (rs3025039)." (PMID 31646966, 2019). "The vascular endothelial growth factor A (VEGF-A) has been related with occurrence of pregnancy pathologies such as preeclampsia." (PMID 25821470, 2015). "Gene expression studies from chorionic villous sampling in women who subsequently developed preeclampsia demonstrated an increasing expression of VEGFA and a decreasing expression of PGF." (PMID 25165809, 2014). "CircRNA_06354 might promote early-onset preeclampsia in humans via the actions of hsa-miR-92a-3p/vascular endothelial growth factor-A (VEGF-A)." (PMID 38674114, 2024). "As shown in our data, ox-LDL–treated HTR8/SVneo cells exhibited preeclampsia-like phenotypic changes: declined migration, impaired angiogenesis (VEGFA was downregulated and FLT1 upregulated), and apoptosis (Bax was upregulated), which were in accordance with the expression in the PE placenta." (PMID 34568425, 2021). "Modulating VEGFA or other signaling pathways involved in trophoblast regulation could offer strategies for correcting defective placentation or managing conditions like preeclampsia and placenta accreta spectrum disorders." (PMID 40710304, 2025). "Therefore, we have concluded that the higher expression of miR‐195‐5p in endothelial cell cultures incubated with preeclampsia plasma may contribute to decreased expression of VEGFA (gene and protein) and increased antiangiogenic status in preeclampsia." (PMID 27012926, 2016). "Based on our RT-qPCR results, VEGFA and CTGF mRNA levels were significantly higher in SLE placentas, suggesting that placental angiogenic activity is disrupted in SLE, just like in preeclampsia." (PMID 35372436, 2022). "Preeclampsia also promoted TNF-α-, TGFβ1-, and VEGFA-induced proliferation of HUVEC from female offspring, but not in HUVEC from male offspring." (PMID 36420416, 2022). "Patients with preeclampsia also showed elevated levels of the proteins transforming growth factor-β (TGF-β), vascular endothelial growth factor A (VEGFA), and angiotensinogen in their cerebral spinal fluid." (PMID 36324311, 2022). "In this study, we found that autophagy is repressed, trophoblast apoptosis is enhanced (Bax was upregulated), and angiogenesis is impaired (VEGFA was downregulated, and FLT1 was upregulated) in preeclampsia." (PMID 34568425, 2021). "The findings above present us with a rational hypothesis that autophagy activation accompanied by the changes of VEGFA and FLT1 could affect trophoblasts’ migration ability and protect against apoptosis under an ox-LDL–mediated preeclampsia-like condition." (PMID 34568425, 2021). "Although various studies have reported an association of SNVs with preeclampsia, the role of F5, MTHFR and VEGFA gene variants in Pakistani preeclamptic women have not been determined yet." (PMID 31646966, 2019). "We designed a series of experiments to show that autophagy activated by hypoxia could protect against the ox-LDL–mediated preeclampsia-like phenotype in HTR8/SVneo cells: migration declined, apoptosis (Bax was upregulated), and impaired angiogenesis (VEGFA was downregulated and FLT1 upregulated)." (PMID 34568425, 2021). "We confirmed that autophagy-related genes (LC3B and Beclin1) and VEGFA were downregulated, while Bax and FLT1 were upregulated in placentas from preeclamptic women, indicating that the autophagy pathway might play a significant role in preeclampsia." (PMID 34568425, 2021).